SEC11A (SEC11 homolog A, signal peptidase complex subunit)
Description:
Catalytic component of the signal peptidase complex (SPC) which catalyzes the cleavage of N-terminal signal sequences from nascent proteins as they are translocated into the lumen of the endoplasmic reticulum. Specifically cleaves N-terminal signal peptides that contain a hydrophobic alpha-helix (h-region) shorter than 18-20 amino acids.
Synonyms: SEC11L1; SPC18; SPCS4A; sid2895; 1810012E07Rik
Tractability: Antibody: UniProt predicts a signal peptide or a membrane-spanning region. PROTAC: ubiquitination databases record sites on it; its protein half-life has been measured.
Target class: Enzyme; Hydrolase
Gene: Protein-coding gene on chromosome 15 (84,669,529 to 84,716,460, reverse strand). Ensembl gene ENSG00000140612.
Subcellular location: Endoplasmic reticulum membrane
Subcellular location (Human Protein Atlas): Nuclear membrane; Golgi apparatus
Pathways (Reactome):
Metabolism of proteins: SRP-dependent cotranslational protein targeting to membrane; Synthesis, secretion, and deacylation of Ghrelin; Synthesis, secretion, and inactivation of Glucagon-like Peptide-1 (GLP-1); Synthesis, secretion, and inactivation of Glucose-dependent Insulinotropic Polypeptide (GIP)
Disease: Maturation of DENV proteins; Maturation of hRSV A proteins
Cell-Cell communication: Regulation of CDH1 posttranslational processing and trafficking to plasma membrane
Gene Ontology:
Molecular function: protein binding; serine-type endopeptidase activity; signal peptidase activity; peptidase activity
Biological process: protein maturation; protein processing; response to virus
Cellular component: endoplasmic reticulum membrane; signal peptidase complex; membrane
Genetic constraint (gnomAD): Loss-of-function variants: 7 observed, 14.06 expected, observed/expected ratio (o/e) 0.5, 90% interval 0.28 to 0.94. The upper end of that interval is the gene's LOEUF score, 0.94, which puts it in group 3 of 6, group 1 being the genes least tolerant of losing a copy. Missense variants: 89 observed, 127.15 expected, observed/expected ratio (o/e) 0.7, 90% interval 0.59 to 0.83. Synonymous variants: 44 observed, 41.38 expected, observed/expected ratio (o/e) 1.06, 90% interval 0.83 to 1.37.
Homologues: Orthologues: pig SEC11A (100% identical), tropical clawed frog sec11a (97% identical), zebrafish sec11a (97% identical), mouse Sec11a (93% identical), rabbit SEC11A (93% identical), chimpanzee SEC11A (92% identical), rat Sec11a (92% identical), guinea pig SEC11A (91% identical), Drosophila melanogaster twr (74% identical), Caenorhabditis elegans sec-11 (71% identical). Paralogues in human: SEC11C (79% identical).
Diseases named in the same sentence as SEC11A in open-access papers:
SEC11A is named in the same sentence as 18 diseases in open-access papers, as found by Europe PMC text mining. Sharing a sentence is not in itself a finding about the gene and the disease. The quoted sentences say what the papers report.
gastric cancer (4 papers, 2018 to 2024). A primary or metastatic malignant neoplasm involving the stomach. "SEC11A was SEC11 homolog A, signal peptidase complex subunit, and it is a protein coding gene linked to cell migration and invasion, gastric cancer, and lymph node metastasis." (PMID 30552317, 2018). "The SEC11A gene encodes the signal peptidase complex 18, which contributes to malignant progression via promotion of transforming growth factor alpha secretion in gastric cancer." (PMID 39002029, 2024). "Similarly, the 3’ UTR of SEC11A gene was significantly shorter than that of normal cells, but it was previously reported that SEC11A gene was overexpressed in gastric cancer." (PMID 36816917, 2023). "Therefore, the overexpression of SEC11A in gastric cancer cells may be related to the emerging APA sites." (PMID 36816917, 2023).
schizophrenia (2 papers, 2022 to 2023). A major psychotic disorder characterized by abnormalities in the perception or expression of reality. "Sec11a, a candidate gene for total distance in the center zone, is associated with depression and schizophrenia." (PMID 35237186, 2022). "As expected because of low sensitivity, this study identified only seven placental genes associated with schizophrenia, three of which are nonetheless replicated in our dataset (COQ10B, placenta-specific, and VPS29 and SEC11A, also associated with schizophrenia in brain)." (PMID 37188697, 2023).
tongue squamous cell carcinoma (2 papers, 2022). A squamous cell carcinoma that arises from the tongue. "One recent study found that inhibiting SEC11A can reduce proliferation, migration, and invasion and induce apoptosis of tongue squamous cell carcinoma, suggesting a potential oncogenic role of this gene in head and neck squamous cell carcinoma." (PMID 35653344, 2022). "By performing immunofluorescent staining in a tongue squamous cell carcinoma cell line (SCC9) and a laryngeal squamous cell carcinoma cell line (TU212), we observed SEC11A expression in the nucleus membrane and cytoplasm." (PMID 35653344, 2022).
head and neck squamous cell carcinoma (1 paper, 2022). A squamous cell carcinoma that arises from any of the following anatomic sites: lip and oral cavity, nasal cavity, paranasal sinuses, pharynx, larynx, and salivary glands. "Since head and neck squamous cell carcinoma is a group of heterogeneous tumors with different anatomic origins, we compared SEC11A expression among different anatomic subgroups." (PMID 35653344, 2022). "In summary, SEC11A upregulation is a result of gene amplification in head and neck squamous cell carcinoma." (PMID 35653344, 2022). "In this study, we revealed that SEC11A upregulation is a result of gene amplification in head and neck squamous cell carcinoma." (PMID 35653344, 2022). "Via IHC staining of SEC11A in a commercial head and neck squamous cell carcinoma tissue array, we confirmed a similar subcellular location of SEC11A in immunofluorescent staining." (PMID 35653344, 2022). "Therefore, we hypothesized that SEC11A might also modulate the malignant behaviors of head and neck squamous cell carcinoma via other mechanisms." (PMID 35653344, 2022). "Since HPV positive and HPV negative head and neck squamous cell carcinoma tumors have distinct molecular profiles and biological behaviors, we further assessed whether SEC11A expression is consistently associated with PFS and DSS in these subgroups." (PMID 35653344, 2022). "In the current study, we aimed to investigate the expression of the five microsomal signal peptidase complex (SPC) subunit genes (SEC11A, SEC11C, SPCS1, SPCS2, and SPCS3) in head and neck squamous cell carcinoma (HNSC) and to explore their prognostic value." (PMID 35653344, 2022).
cancer (4 papers, 2022 to 2023). A tumor composed of atypical neoplastic, often pleomorphic cells that invade other tissues. "By setting r>|0.2| as the cutoff, we found that SEC11A expression was negatively correlated with CD8+ T cells and B cells, but was positively correlated with cancer-associated fibroblast and myeloid-derived suppressor cells (MDSCs)." (PMID 35653344, 2022). "SEC11A expression was negatively correlated with CD8+ T cells and B cells, but was positively correlated with cancer-associated fibroblast and myeloid-derived suppressor cells (MDSCs) in the tumor microenvironment." (PMID 35653344, 2022). "The protein levels of SEC11A and CYB5B were significantly increased in cancer tissues." (PMID 35573741, 2022).
tumor (3 papers, 2021 to 2022). "Therefore, we infer that SEC11A associated elevation of the oxidative phosphorylation genes might generate a favorable tumor microenvironment for the infiltration or conversion of MDSCs." (PMID 35653344, 2022). "Using single-cell RNA-seq data from one previous publication, we checked SEC11A expression in the tumor microenvironment." (PMID 35653344, 2022). "Using data from one previous single-cell RNA-seq database, we found that SEC11A is expressed not only in tumor cells, but also in other cells in the tumor microenvironment." (PMID 35653344, 2022). "Gene set enrichment analysis (GSEA), and immune cell infiltration analysis were performed to check the influence of SEC11A on the tumor microenvironment." (PMID 35653344, 2022). "By checking immune cell abundance in the tumor microenvironment, we observed a significant positive correlation between SEC11A expression and the infiltration of MDSCs, a group of immature myeloid cells with immunosuppressive effects." (PMID 35653344, 2022). "SEC11A is expressed in all subtypes of cells in the tumor microenvironment." (PMID 35653344, 2022). "In our analysis, EIF4EBP1, IMP3, ATF3, SEC11A and SHC1 also exhibited different expression between BC and non-tumour samples, and were significantly associated with the tumour type, invasive progression, or tumour grade (SupplementaryFigure S2)." (PMID 34187252, 2021). "Besides, SEC11A expression might predict the infiltration of certain types of immune cells in the tumor microenvironment." (PMID 35653344, 2022). "Results showed that SEC11A, SPCS2 and SPCS3 were significantly upregulated in the tumor group than in the normal group." (PMID 35653344, 2022).
SEC11A also shares sentences with these, for which no sentence is quoted: attention deficit-hyperactivity disorder (1 paper); autism spectrum disorder (1); bipolar disorder (1); breast carcinoma (1); depression (1); generalized anxiety disorder (1); laryngeal squamous cell carcinoma (1); lymph node metastasis (1); mental disorder (1); obsessive-compulsive disorder (1); parathyroid adenoma (1); unipolar depression (1).